BCL2 (BCL2 apoptosis regulator)
Diseases named in the same sentence as BCL2 in open-access papers (continued):
Sharing a sentence is not in itself a finding about the gene and the disease.
glioma (continued). "Moreover, Sch B induces cell cycle arrest of glioma cells in the G0/G1 phase, triggers apoptosis through the activation of caspase-3, caspase-9, poly (ADP-ribose) polymerase (PARP), and Bcl-2, and significantly inhibits the tumor growth of glioma cells in vivo." (PMID 39995410, 2025). "The results of immunoblotting showed that co-culture with HMC3 significantly increased the expression of CD44 in glioma cells, thereby activating the PI3K/AKT signaling pathway, leading to a significant downregulation of Bax and cleaved-caspase 3, and a significant upregulation of Bcl-2." (PMID 39143438, 2024). "To this end, we examined the expression of key components of the core apoptotic machinery implicated in cancer cell survival, namely the BCL2 and IAP families, in three pairs of the glioma stem cell line and its matched non-stem cell counterpart treated with RG7112." (PMID 38612758, 2024). "Furthermore, in our correlation analysis, we found that miR-384 was negatively correlated with Bcl-2 and LINC01087, which suggested that LINC01087/miR-384/Bcl-2 axis might exist in glioma progression." (PMID 34459789, 2021). "Finally, Bcl-2 is a crucial target of cell drug resistance, and whether LINC01087/miR-384/Bcl-2 axis has the same effect in glioma drug resistance needs further verification." (PMID 34459789, 2021). "Moreover, silencing of S100A12 also caused the up-regulation of the protein expression of cleaved caspase 3 and Bax and down-regulation of Bcl2.These results indicated that S100A12 might contribute to the proliferation and apoptosis of glioma cells." (PMID 32228516, 2020). "Similarly, miR-136-5p could enhance glioma cell apoptosis via targeting MTDH (Metadherin) and Bcl-2." (PMID 32677950, 2020). "Furthermore, experiments showed that brucine could reduce the expression of Bcl-2 and COX-2 in U251 glioma cells, up-regulate the expression of Bax, reduce the survival rate of glioma cells, and inhibit the growth of the xenografts in vivo." (PMID 32308621, 2020). "In addition, Bcl-2, Bcl-xL and caspase 3 were also the downstream of PIWIL4 and thence CRNDE could interfere with glioma cells apoptosis through CRNDE-miR-384-PIWIL4 axis." (PMID 32435153, 2020). "Finally, by analyzing the relationship of protein levels amongst Bax, Bcl-2, Beclin-1, and the caspase family proteins, it was confirmed that long-term treatment with ING4 can induce parallel pathways of both autophagy and apoptotic cell death in glioma cells." (PMID 30643005, 2019). "Our results verified that ALO could target the anti-apoptotic protein Bcl-2 in glioma cells but not in other cancer cells." (PMID 31534865, 2019). "The increased level of miR‐497 in TMZ‐resistant glioma cells was concurrent with the up‐regulation of insulin‐like growth factor 1 receptor (IGF1R)/insulin receptor substrate 1 (IRS1) pathway‐related proteins, that is, IGF1R, IRS1, mammalian target of rapamycin (mTOR), and Bcl‐2." (PMID 28064447, 2017). "At this point, it has not entirely unraveled whether gliomas of proneural subtype are particularly prone or resistant to Bcl-2/Bcl-xL inhibition." (PMID 26474387, 2015). "However, in drug resistant gliomas Bax does not translocate, and overexpression of Bcl-2 conveys resistance to staurosporine induced apoptosis." (PMID 24847208, 2014). "Our results revealed that a knockdown of SATB1 in highly aggressive glioma U251 cells could alter the expression of c-Met, SLC22A18, caspase-3 and bcl-2 protein, reversing tumorigenesis, inhibiting tumor growth, invasion and angiogenesis, and inducing apoptosis." (PMID 22839214, 2012). "Interestingly, lncRNA growth arrest-specific 5 (GAS5) functions as a tumor suppressor in glioma cells by alleviating the promoter methylation of miR-424, and consequently increasing the expression of miR-424, and suppressing AKT3 and its targets, cyclinD1, c-Myc, Bax, and Bcl-2." (PMID 37998329, 2023).
glioma (continued). "When glioma cells were transfected with si-LINC02587 as opposed to si-NC, Bcl-2 expression levels were dramatically decreased and Bax expression levels were significantly enhanced." (PMID 37848823, 2023). "One publication postulates that the inhibition of Mcl-1, but not the simultaneous inhibition of Bcl-2, Bcl-w, and, Bcl-xL with ABT-737 sensitizes glioma cells to TMZ42." (PMID 36273072, 2022). "Hyp cytotoxicity was low in human U87 MG glioma, similar to that of ABT263, where Goss exerted sufficient cytotoxicity, suggesting that Hyp acts primarily on Bcl-2, but not on Mcl-1 protein." (PMID 36267274, 2022). "Bcl-2 is typically not expressed in the cortex of non-TBI patients post-mortem, after epilepsy resections, and near glioma margins." (PMID 32570722, 2020). "They found that expression levels of Bcl-2 and Nur-77 in TBI patients were both significantly upregulated (p < 0.001) and positively correlated (r = 1.051, p < 0.001) when compared to glioma patients, though these levels were non-zero in glioma." (PMID 32570722, 2020). "A previous study revealed that the suppression of CLIC4 enhanced the apoptosis induced by H2O2 in glioma C6 cells along with the dissipation of the mitochondrial membrane potential and nuclear translocation of CLIC4 but without the change of Bax/Bcl-2 ratio." (PMID 26816615, 2016). "Other treatment options, like hypomethylating drugs and BCL2 inhibitors, are commonly used to treat IDH-mutant hematologic malignancies like acute myeloid leukemia (AML) but have not been formally studied in the treatment of IDH-mutant gliomas." (PMID 38957232, 2024). "However, a study on glioma cells demonstrated no suppression of XIAP protein despite induction of apoptosis, suggesting suppression of other antiapoptotic molecules such as Bcl2 and Bcl-XL in these cells." (PMID 26347311, 2015).
B-cell lymphoma (400 papers, 1994 to 2026). "BCL-2 overexpression is commonly associated with tumor survival and metastatic progression in B-cell lymphoma and breast and pancreatic cancers." (PMID 40392781, 2025). "Concurrent rearrangements of MYC and BCL2 are hallmark alterations in aggressive B-cell lymphomas, also known as double-hit lymphomas, which are classified as high-grade B-cell lymphomas (HGBCLs)." (PMID 41301875, 2025). "The BCL-2-associated X protein (BAX) to B-cell Lymphoma/Leukemia (BCL2) ratio was assessed by qRT-PCR." (PMID 41354896, 2025). "For instance, it was shown that the polymorphism in the 3’UTR binding region of the BCL-2 gene, targeted by let-7b, in B-cell lymphoma was associated with fluorouracil resistance of hepatocellular carcinoma." (PMID 39787178, 2025). "The roles of BCL2 family members in B-cell lymphoma-associated apoptosis were discovered in the 1980s, with BCL2 exerts anti-apoptotic effects that promote cancer development and progression." (PMID 38361755, 2024). "Major oncogenes frequently associated with particular types of B-cell lymphoma are BCL2 (FL, DLBCL), BCL6 (DLBCL), CCND1 (MCL, MM), and MYC (BL, DLBCL)." (PMID 37371852, 2023). "Overexpression of the antiapoptotic molecule B-cell lymphoma 2 (BCL-2) in B-cell lymphoma/leukemia cells is commonly associated with decreased patient survival." (PMID 36768665, 2023). "In this case, the finding of CD20 and bcl‐2 positive lymphocytes invading Hassall bodies and thymic epithelial cells led to the definitive diagnosis of primary thymic extranodal marginal‐zone B‐cell lymphoma of mucosa‐associated lymphoid tissue type." (PMID 37082169, 2023). "The Bcl2 gene is exclusively expressed in B cell lymphoma cell line and associates with a stripe that spans the entire gene body." (PMID 35332165, 2022). "Particularly, it is required for the definition of the high-grade B-cell lymphoma with MYC associated to BCL2 and/orBCL6 rearrangements." (PMID 33768318, 2021). "Immunohistochemistry analysis of Bcl-2-associated X protein (Bax) and B-cell lymphoma/leukemia-2 (Bcl-2) was carried out." (PMID 32714412, 2020). "Bcl2 has long been associated with drug resistance since its discovery as a proto-oncogene in non-Hodgkin's B-cell lymphomas, and over the years, it has been extensively studied as a potential target for cancer therapy." (PMID 22069448, 2011). "A proteome profiling carried out on BRCA1-mutated W780 and W0069 cells evidenced that CDDO-Im significantly increases caspase 3 cleavage, increases heat shock protein 70 (HSP70), and decreases in claspin, BIRC5, B-cell Lymphoma-extra-large, and BCL2 associated agonist of cell death." (PMID 40136510, 2025). "However, the variation in BCL2 positivity was potentially due to the B‐cell lymphoma heterogeneity or the BCL2 mutation altering the immunohistochemical binding site epitope of the antibody." (PMID 40356256, 2025). "Factors associated with worse PFS were otherwise identical with those associated with worse OS, and included high grade B cell lymphoma with Myc/Bcl2 translocations (p<0.03), higher IPI (p<0.001), more lines of therapy received (p<0.001), and not experiencing CR (p<0.001, median OS of 15 months)." (PMID 39324011, 2024). "Lastly, the expression levels of glyceraldehyde-3-phosphate dehydrogenase (GAPDH), cleaved caspase-9, cytochrome C (Cyt-C), B cell lymphoma/leukemia-2 (Bcl-2), B cell lymphoma/leukemia-2 associated X (Bax), AKT, p-AKT, PI3K, and p-PI3K were analyzed utilizing western blotting." (PMID 35414825, 2022). "An ABT-737-induced reduction in maximal O2 consumption was also detectable in SP53, JeKo-1, and WEHI-231 B-cell lymphoma cell lines, with sensitivity correlating with BCL-2:MCL-1 ratio and with susceptibility (SP53 and JeKo-1) or resistance (WEHI-231) to ABT-737-induced apoptosis." (PMID 22880001, 2012).
B-cell lymphoma (continued). "We detect EZH2 mutations in a significant proportion of BCL2-rearranged follicular lymphomas, BCL2-rearranged diffuse large B cell lymphomas, and high-grade B cell lymphomas with concurrent BCL2 and MYC rearrangements (so-called “double-hit lymphomas”), but not in BL." (PMID 22194861, 2011). "Immunohistochemistry revealed CD20(+), PAX5(+), BCL2(+), and monoclonal IgH rearrangement, consistent with low-grade B-cell NHL, most likely extranodal marginal zone lymphoma (ENMZL), non-gastric/non-cutaneous type." (PMID 41800064, 2026). "Immunohistochemical findings showed that Cyt increased 8-hydroxydeoxyguanosine (8-OHdG) and B-cell lymphoma/leukemia-2-associated X protein (Bax) expression, whereas it downregulated Glutathione peroxidase 4 (GPX4) and B-cell lymphoma/leukemia-2 (Bcl-2)." (PMID 41726560, 2026). "High-grade B-cell lymphomas expressing Myc, Bcl2, and Bcl6 proteins, known as “triple expressors,” are associated with aggressive behaviour and poor prognosis." (PMID 40941668, 2025). "The IGH locus is a frequent translocation partner for MYC and BCL2 genes in B-cell lymphomas, driving oncogenic overexpression that promotes uncontrolled proliferation (MYC) and inhibits apoptosis (BCL2)." (PMID 41301875, 2025). "In comparison, CR rates were 53% among those with high-grade B-cell lymphoma featuring BCL2 rearrangement and 25% in other DLBCL subtypes." (PMID 40805213, 2025). "Diffuse large B-cell lymphoma/high grade B-cell lymphoma withMYC andBCL2 rearrangements (DLBCL/HGBL-MYC/BCL2)." (PMID 38835967, 2024). "Zanubrutinib is a BTK inhibitor reported to be effective for B‐cell lymphomas with MYD88 and CD79b mutations, double expression of MYC and BCL2/BCL6, and CD5 expression." (PMID 39054569, 2024). "Research has revealed that some NHL patients, especially B-cell lymphoma patients, overexpress BCL-2, which promotes tumor cell resistance to chemotherapy drugs and is associated with poor prognosis." (PMID 39060763, 2024). "The Bcl-2 inhibitor, venetoclax, is a BH-3 mimetic compound and is a potent inhibitor of Bcl-2 function, resulting in apoptosis of aberrant B-cell lymphoma cells." (PMID 38792015, 2024). "When injected into the Prdm1.fl/Myd88/Bcl2 mice after they had developed their autochthonous B cell lymphomas, mCAR and mCAR/mCCR cells prevented tumor growth in most mice." (PMID 38340727, 2024). "Although Bcl2 was initially identified as a cancer gene, its anti-apoptotic properties were found to enhance B-cell lymphoma proliferation." (PMID 38396011, 2024). "Despite being a defining feature of LBCL‐IRF4‐R, IRF4 rearrangement is not exclusive to this subtype, as it can also occur in other aggressive B‐cell lymphomas, particularly those associated with MYC or BCL2 rearrangements." (PMID 39415926, 2024). "Although BCL2 was originally identified as an anti-apoptotic gene in B-cell lymphomas, it was later shown to suppress apoptosis in a variety of cell systems, including neural and other cell types." (PMID 36937440, 2023). "Cases harbouring both MYC and BCL2 rearrangements are better classified as high-grade B cell lymphoma (HGBCL) with MYC and BCL2 rearrangement." (PMID 36278991, 2023). "The pro-survival BCL-2 was initially discovered for its role in B-cell lymphoma, hence its name B-cell lymphoma 2, and it was shown to contribute to tumor initiation and progression." (PMID 36795726, 2023).
B-cell lymphoma (continued). "High-grade B-cell lymphoma with translocations of MYC and BCL2 and/or BCL6 genes has been associated with a worse prognosis, whereas mutations such as MYD88 and CD79B have been frequently described in PCNSL." (PMID 37240953, 2023). "BCL2 is a prominent target of cutting‐edge treatment strategies for cancer and other disorders and was initially discovered through genetic research of B cell lymphomas." (PMID 37700495, 2023). "Major changes have been made in the diffuse large B-cell lymphomas (DLBCL)/high-grade B-cell lymphomas (HGBL) associated with MYC and BCL2 and/or BCL6 rearrangements." (PMID 37190213, 2023). "In WHO-HAEM5, tumors with MYC and BCL2 rearrangements are named diffuse large B-cell lymphoma/high-grade B-cell lymphoma with MYC and BCL2 rearrangements (DLBCL/HGBCL MYC/BCL2)." (PMID 36460764, 2023). "Since it has been found that IRF4 rearrangement can occur in some other aggressive B‐cell lymphomas as well, especially those which are associated with MYC or BCL2 rearrangement, mainly in adults." (PMID 37081786, 2023). "Equal to venetoclax, the BCL-2 inhibitor ABT-737 was found to potentiate CAR-T-cell cytotoxicity against selected B-cell lymphoma cell lines resistant to apoptosis, underscoring the advantage of combinatorial targeting of CAR-T cells and small molecules." (PMID 36768665, 2023). "We also showed that BCL2 is upregulated (q = 7.10 × 10−16), which is known to be upregulated in other B-cell lymphomas." (PMID 37910143, 2023). "High‐grade B‐cell lymphomas with double or triple hits (MYC plus BCL2 and/or BCL6 genes rearrangements) (HGBL‐DH/TH) are usually highly aggressive lymphomas that respond poorly to conventional chemotherapeutic regimes." (PMID 35846201, 2022). "B-cell lymphoma (BCl) is a family of key apoptotic proteins including anti-apoptotic proteins (Bcl-2 and Bcl-xL) and pro-apoptotic proteins (Bax and Bak)." (PMID 35807546, 2022). "BCL-2 is highly expressed in B-cell lymphomas, and a great majority of these cells are dependent on BCL-2 for survival." (PMID 36167829, 2022). "Interestingly, in a previous study the prevalence of BCL2 mutations detected in FL tumor tissue samples was 12% at diagnosis and 53% at the transformation; and FL patients with BCL2 mutations had shortened survival and increased risk of histological transformation to aggressive B cell lymphomas." (PMID 35795062, 2022). "This family of proteins was named after the typical member Bcl-2, which was named for its discovery and abnormal expression in B-cell lymphomas." (PMID 35216310, 2022). "High-grade B-cell lymphomas (HGBLs), with c-Myc, Bcl2, and/or Bcl6 rearrangement, are aggressive neoplasms with poor clinical outcomes." (PMID 36312606, 2022). "HGBL-DH/TH (high grade B-cell lymphoma with double/triple hits) harbor simultaneous translocations of MYC and BCL2 (DHL BCL2) or MYC and BCL6 (DHL BCL6), which associate with aggressive clinical course and inferior prognosis." (PMID 35884496, 2022). "The WHO classification of lymphoid neoplasms further categorizes HGBL with the addition of a new term, "high-grade B-cell lymphoma with c-Myc, Bcl2, and/or Bcl6 rearrangement"." (PMID 36312606, 2022). "DHITsig positivity was determined by overexpression of genes of high-grade B-cell lymphoma double hit or triple hit with BCL2 translocations." (PMID 35454765, 2022). "It is especially active against aggressive MYC+/BCL2+ B cell lymphomas and this likely reflects the eIF4A-dependent translation of both MYC and BCL2." (PMID 33562682, 2021). "Bcl-2 inhibitor with bevacizumab is currently an effectively therapeutic strategy to treat B-cell NHL." (PMID 33505491, 2021). "Chromosomal rearrangements commonly occur in B-cell lymphomas, mainly involving BCL2 gene at 18q21 chromosomal locus, BCL6 at 3q27 and MYC at 8q24." (PMID 33768318, 2021). "Regulation of the anti-apoptotic BCL2 protein determines cell survival and is frequently abnormal in B cell lymphomas." (PMID 33914737, 2021).